FAP (fibroblast activation protein alpha)
Diseases named in the same sentence as FAP in open-access papers (continued):
Sharing a sentence is not in itself a finding about the gene and the disease.
tumor (continued). "Fibroblast activation protein (FAP) is a type II membrane-bound glycoprotein from the dipeptidyl peptidase 4 family, highly expressed in cancer-associated fibroblasts (CAFs) and tumor cells of many cancers." (PMID 39963103, 2025). "Changes in FAP expression have been linked to the β-catenin signaling pathway and thus potentially protects tumor cells from chemotherapy-induced apoptosis." (PMID 41373408, 2025). "FAP has been considered a promising therapeutic target since FAP positive (FAP+) CAFs are linked to immunosuppressive tumor microenvironments and correlate with worse prognoses in solid tumor cancers." (PMID 41228205, 2025). "For example, CAFs often exhibit the overexpression of FAPα (fibroblast-associated protein alpha), a key marker linked to tumour progression and metastasis." (PMID 40083695, 2025). "The expression levels of immune checkpoints, including BTLA, VTCN1, CD276, PDCD1, CD160, NRP2, and CD200, as well as the tumor-associated fibroblast marker FAP, were found to be higher in the high-risk group." (PMID 40364849, 2025). "FAP+ CAFs were negatively associated with intratumoral TLSs, suggesting that tumor immunosuppression occurs via the inhibition of TLS cluster formation and plasma cell maturation." (PMID 41154405, 2025). "Fibroblast activation protein-α (FAP), a marker of activated cancer-associated fibroblasts (CAFs), has emerged as a potential indicator of tumor aggressiveness and resistance to systemic therapies in various solid tumors." (PMID 41303595, 2025). "This study aimed to develop an Al18F-labeled FAP-targeted tracer and explore the diagnostic value in acquired drug-resistant tumor models." (PMID 40430845, 2025). "Researchers have found that increased percentages of FAP + CAFs were associated with bigger tumours, synchronous metastases and tumour aggression based on multiplex immunofluorescence analysis." (PMID 40375605, 2025). "In this study, we used 18F-labeled FAP as a complementary imaging agent and validated its diagnostic utility in an acquired drug-resistant tumor model, offering a novel perspective for personalized PCa treatment." (PMID 40430845, 2025). "FAP, a type II transmembrane serine protease glycoprotein, is prominently overexpressed on cancer-associated fibroblasts (CAFs) within the tumor-associated stroma across multiple human epithelial malignancies." (PMID 41455698, 2025). "Fibroblast activation protein (FAP), a membrane-bound serine protease enriched in tumor-associated stroma, is widely used due to its minimal expression in normal adult tissues and its role in matrix remodeling and immune modulation." (PMID 41441395, 2025). "Fibroblast activation protein (FAP) is predominantly expressed in cancer‐associated fibroblasts within the tumour stroma of 80%–90% of cancers, playing a pivotal role in modulating tumour behaviour." (PMID 39956945, 2025). "Fibroblast activation protein (FAP) is a transmembrane protein that is overexpressed in cancer-associated fibroblasts within multiple tumor types with minimal expression in normal tissues." (PMID 41301015, 2025). "Among these, FAP+CAFs have been implicated in promoting tumor progression and modulating the immune response." (PMID 40843362, 2025). "Consistently, silencing FAP in CAFs was associated with impaired tumour-promoting effects in preclinical studies." (PMID 39780187, 2025). "FAP is highly expressed in tumor-associated myofibroblasts and is associated with remodeling of the extracellular matrix." (PMID 40869109, 2025). "FAP, a type II transmembrane glycoprotein belonging to the dipeptidyl peptidase family, is highly expressed in cancer-associated fibroblasts within the tumor microenvironment." (PMID 40950982, 2025). "Fibroblast activation protein (FAP) is a type II transmembrane serine protease predominantly expressed on the surface of cancer-associated fibroblasts (CAFs) in the tumor stroma." (PMID 40777126, 2025).
tumor (continued). "We employed an integrative approach combining bulk RNA sequencing, single-cell RNA sequencing (scRNA-seq), and spatial transcriptomics to investigate interactions between FAP+ fibroblasts and tumor-associated macrophages in PCa." (PMID 40438108, 2025). "We generated trifunctional antibody-cytokine fusion proteins composed of a scFv antibody directed against the fibroblast activation protein (FAP) as a tumor associated model antigen, IL-15 fused to an IL-15Rα fragment (RD), and either IL-7 or IL-21." (PMID 40370435, 2025). "Inhibition of FAP increased the immune-evasive features of TC cells and CAFs associated with characteristics resembling a “cold” tumor but reducing the motility indicating a potential therapeutic favorable exchange." (PMID 41233863, 2025). "In conclusion, FAP-positive cancer-associated fibroblasts (CAFs) are pivotal in orchestrating the complex interplay within the tumour microenvironment that crucially influences cancer progression." (PMID 40741380, 2025). "Simlukafusp alfa is an immunocytokine that binds FAP on tumour-associated fibroblasts and enhances immune cell activity by increasing antibody-mediated cytotoxicity through PD-L1 checkpoint inhibition." (PMID 40741380, 2025). "[68Ga] and [18F]–labeled fibroblast activation protein inhibitor (FAPI) PET serves as an advanced imaging technique that targets cancer-associated fibroblasts within tumor stroma, which are known for their high expression of FAP." (PMID 39384589, 2025). "In a study of 171 GC patients receiving neoadjuvant chemotherapy (NCT), FAP-positive CAFs were significantly associated with poor tumor regression grade (TRG) (P < 0.01) and worse overall survival in univariate analysis (P < 0.05)." (PMID 41244835, 2025). "Several recent reports have evaluated the tumor diagnostic potential of FAP immunostaining in intrathoracic SFTs." (PMID 40126602, 2025). "68Ga-labelled FAPI PET specifically targets FAP, which is highly expressed by cancer-associated fibroblasts in the tumour stroma." (PMID 39858014, 2025). "A significant study focusing on FAP+ fibroblasts identified tumor-specific macrophages that were highly associated with FAP+ fibroblasts, namely SPP1+ TAMs." (PMID 40191203, 2025). "Upon reaching the tumor site and contacting CAFs, FAP-α cleaves the peptide chain, causing NP dissociation into ~20 nm small particles." (PMID 41154598, 2025). "These nanovesicles were able to induce the strong immune response of specific CTLs against FAP+ tumor cells and cancer-associated fibroblasts (CAFs), which contributed to the reprogramming of the immunosuppressive tumor microenvironment." (PMID 40006583, 2025). "Tumour stroma with high FAP expression has been linked to poorer outcomes, making it a suitable candidate for targeted therapy." (PMID 40379112, 2025). "FAP is highly expressed in tumor-associated fibroblasts and plays a pivotal role in tumor growth, dissemination, and immune escape." (PMID 40607439, 2025). "68Ga-radiolabeled inhibitor of FAP (FAPI)-PET/CT has been widely used in clinical diagnostic imaging to visualize CAFs in over 20 tumor types." (PMID 40296919, 2025). "A study including 59 patients with NSCLC reported that elevated FAP expression was associated with poor tumor differentiation (p = 0.06)." (PMID 40805245, 2025). "FAP is widespread in the subpopulation of cancer‐associated fibroblasts (CAFs) in many epithelial cancers, which plays a pivotal role in tumor maintenance, growth, and migration." (PMID 40384987, 2025). "FAP is upregulated in tumor cells and cancer-associated fibroblasts (CAFs) within the tumor stroma, but is not expressed in adult somatic tissue." (PMID 41345672, 2025). "In contrast, the frequent and high expression of FRα in tumor cells and FAP in tumor-associated stromal cells suggests that FRα- and FAP-targeted radiopharmaceuticals hold promise for the treatment of advanced-stage EOC." (PMID 41466165, 2025).
tumor (continued). "Although older studies have suggested off-tumour/on-target complications associated with FAP ablation due to muscle and bone marrow expression, recent selective targeting in animal models have been more successful." (PMID 40379112, 2025). "This compound demonstrates the growing interest in FAP as a diagnostic and therapeutic target across various tumour types, building upon the clinical validation of other FAP-directed agents." (PMID 40725089, 2025). "Fibroblast activation protein (FAP), highly expressed in cancer-associated fibroblasts and minimally expressed in healthy tissues, represents a compelling and promising target for tumor imaging." (PMID 39604653, 2025). "The fibroblast activation protein (FAP) has emerged as a valuable target due to its high expression in cancer-associated fibroblasts (CAFs) across many tumor types, including HNSCC." (PMID 41258458, 2025). "Further research has increased the number of cancers where FAP is overexpressed and shown that FAP can be found in various elements of the cell microenvironment of the tumor, in addition to cancer-associated fibroblasts." (PMID 41244835, 2025). "Co-culture experiments directly linked tumor cell Pin1 to CAF function: Pin1-knockdown tumor cells reduced FAP expression, and CAFs activated by these cells showed impaired ability to suppress IFN-γ+ CD8+ T cells in PBMC co-cultures." (PMID 41246306, 2025). "In several clinical analyses, FAP+ CAFs are associated with tumor metastasis and poor patient survival." (PMID 40438601, 2025). "FAP-positive cancer-associated fibroblasts (CAFs) play multiple roles in tumour progression and immune modulation." (PMID 40741380, 2025). "Fibroblast activation protein (FAP) is a membrane-bound serine protease highly expressed in cancer-associated fibroblasts (CAFs) within the tumor microenvironment (TME)." (PMID 40283957, 2025). "Caused off-target toxicity by targeting FAPα+ stem cells, resulting in cachexia despite reduced tumor burden." (PMID 40918451, 2025). "One such target is fibroblast activation protein (FAP), a type II transmembrane glycoprotein that is overexpressed in activated cancer-associated fibroblasts within the tumor microenvironment of various epithelial cancers." (PMID 40805245, 2025). "The class of diagnostic FAP-targeting radiopharmaceuticals labeled with gallium-68 (68Ga-FAPIs) has been shown to achieve a high tumor-to-background ratio (TBR) in various malignancies." (PMID 41463267, 2025). "Beyond its role in imaging, FAP expression is closely linked to tumor aggressiveness and prognosis, with higher expression levels often correlating with poorer patient outcomes." (PMID 40283957, 2025). "For instance, the human fibroblast activation protein (FAP), a 97-kilodalton cell surface glycoprotein, is specifically expressed within the context of tumor-associated fibroblasts." (PMID 40485724, 2025). "Our quantitative analysis revealed a significant association between the abundance of FAP + CAFs at the tumor’s periphery and the onset of metastasis." (PMID 39751643, 2025). "In this study, we used FAP to identify and isolate cCAFs as FAP overexpression correlates with higher risk of tumor invasion, lymph node metastasis, decreased overall survival and resistance to therapies." (PMID 38634185, 2025). "FAP is a protease produced by cancer-associated fibroblasts (CAFs) and is involved in the remodeling of the tumor extracellular matrix (ECM)." (PMID 40861448, 2025). "Our study unveils the association of FAP with poor tumor prognosis across multiple cancers and highlights its potential as a therapeutic target in HNSC." (PMID 39055892, 2024). "FAP is a membrane-bound serine protease in the tumor microenvironment and has been shown to be implicated in various pathological conditions including cancer." (PMID 38999044, 2024).
tumor (continued). "One such tumour antigen, fibroblast activating protein‐α (FAP), has garnered attention due to its overexpression in cancer‐associated fibroblasts (CAFs) across more than 90% of human tumour tissues." (PMID 38572668, 2024). "Then, we determined if these observed tumor‐inhibiting effects were associated with CD8+ T cell infiltration inside the tumor tissues by performing IF assays on the excised orthotopic tumor samples to evaluate the protein levels of FAP‐α and CD8." (PMID 38417121, 2024). "This was achieved by clearing FAP + stromal cells, depleting the fibrotic tumor-associated matrix, and reprogramming the immunosuppressive microenvironment." (PMID 38622705, 2024). "In our analysis across TCGA tumor types, differential gene expression analysis revealed that fibroblast activation protein (FAP) is upregulated in tumor tissues and associated with poorer survival rates in HNSCC." (PMID 38826849, 2024). "Although the strategy of increasing the residence time in the tumor by employing homodimeric instead of monomeric FAP inhibitors has proven successful, the underlying molecular basis and mechanism still remain elusive." (PMID 38999044, 2024). "FAP expression was elevated in nine tumor types and was associated with poor survival in eight of them." (PMID 39055892, 2024). "FAP is mainly expressed by cancer-associated fibroblasts in the tumor stroma and less on cancer cells themselves." (PMID 39718718, 2024). "FAP is known to be overexpressed on cancer-associated fibroblasts within the tumour microenvironment of breast, colorectal, ovarian, and other cancers, while its expression is low or undetectable normal tissues." (PMID 39048805, 2024). "The FAP-associated pathways are highly interlinked with the TME-related pathways for tumor progression." (PMID 39579201, 2024). "The kit-prepared [99mTc]Tc-L1, utilized for imaging tumors associated with FAP, demonstrated robust in vitro stability and water solubility, along with notable tumor uptake, specific FAP binding, and favorable target-to-background (TBR) ratios." (PMID 38695960, 2024). "FAP is a type II transmembrane serine protease that is overexpressed by cancer-associated fibroblasts (CAFs) in the tumor microenvironment (TME)." (PMID 38398552, 2024). "Over the last decade, several inhibitors and diagnostic agents targeting the FAP have been developed for tumor diagnosis and treatment." (PMID 39660049, 2024). "Fibroblast activation protein-α (FAP) is the cell-surface antigen expressed by cancer-associated fibroblasts (CAFs) in the tumor microenvironment (TME)." (PMID 39758423, 2024). "FAP, expressed in cancer-associated fibroblasts within the tumor stroma, is targeted to reduce the stroma’s support for tumor growth, with the IL2v component stimulating immune responses for a potentially enhanced therapeutic effect." (PMID 38558814, 2024). "FAP is overexpressed on cancer-associated fibroblasts, which account for most tumor stromata in more than 90% of epithelial carcinomas." (PMID 38272706, 2024). "FAP association with a myriad of cytokines that modulate both tumor behavior and the immune response underscores the necessity for a deeper understanding of its function." (PMID 39035007, 2024). "Fibroblast activation protein (FAP), a transmembrane serine protease overexpressed by cancer-associated fibroblasts in the tumor stroma, is an interesting biomarker for targeted radionuclide theranostics." (PMID 39073475, 2024). "The DAB2+ and SPP1+ tumor-associated macrophages (TAMs) reinforce the function of FAP+ CAFs through signals such as TGF-β, PDGF, and ADM." (PMID 39239526, 2024). "Immunostaining of CRC tissue specimens further revealed that high TRPC5 and FAP expressions were significantly associated with worse tumor regression." (PMID 38817851, 2024). "FAPα is a membrane-bound type 2 serine protease and is highly expressed by cancer-associated fibroblasts (CAFs), but only in low levels by tumor cells or normal tissue." (PMID 39410013, 2024).
tumor (continued). "Some studies have already shown that the high expression of FAP on cancer-associated fibroblasts is strongly associated with aggressive tumor behavior and poor prognoses." (PMID 38176719, 2024). "The tumor-promoting role of FAP was reported earlier; however, there were no published reports on the pan-cancer expression and mutational profiling of FAP to the best of our knowledge." (PMID 39579201, 2024). "FAP is overexpressed in cancer-associated fibroblasts (CAFs) of several tumor entities, such as breast, colon, and pancreatic carcinomas, making it a key target for imaging and, potentially, radiotherapy." (PMID 39661209, 2024). "FAP has also been found to be overexpressed in cancer-associated fibroblasts (CAF) found in the tumor microenvironment of various malignant epithelial tumors such as breast, colon, and pancreatic cancer." (PMID 38505595, 2024). "Fibroblast activation protein (FAP) is the best marker of fibroblasts, is highly expressed in cancer‐associated fibroblasts and a variety of tumour cells, is involved in extracellular matrix remodelling and promotes the migration of stromal and tumour cells." (PMID 39087342, 2024). "The absence of representative animal models with extensive stroma and high FAP expression on cancer-associated fibroblasts led to a low mean tumor-absorbed dose even with high injected activity and consequently to modest survival benefit in this PDAC PDX." (PMID 39266288, 2024). "Recent studies indicate that fibroblast activation protein (FAP) on cancer-associated fibroblasts (CAFs) can promote tumor inflammation and suppress innate and adaptive anti-tumor immunity." (PMID 38558814, 2024). "Fibroblast activation protein (FAP) is highly overexpressed in cancer-associated fibroblasts that are present within the tumor microenvironment." (PMID 38646648, 2024). "This study investigates the role of Fibroblast Activation Protein (FAP)-positive cancer-associated fibroblasts (FAP+CAF) in shaping the tumor immune microenvironment, focusing on its association with immune cell functionality and cytokine expression patterns." (PMID 39035007, 2024). "FAP is commonly targeted with radiotracers such as Fibroblast Activation Protein Inhibitors (FAPIs), which specifically bind to FAP, enabling precise imaging and potential therapeutic intervention in tumor-associated stromal cells." (PMID 39598465, 2024). "Our flow cytometry analysis data indicated that these FAP+CD45+ cells were likely myeloid cells, consistent with previous work demonstrating that macrophages, specifically F4/80high/CCR2+/CD206+ M2 or tumor-associated macrophages (TAMs), express FAP." (PMID 38275890, 2024). "Fibroblast activation protein (FAP), a type-II transmembrane serine protease, is almost exclusively expressed by cancer-associated fibroblasts (CAFs) that are abundantly present in tumor stroma." (PMID 39718718, 2024). "While cancer associated fibroblasts express many markers, 90% of epithelial tumours show increased expression of FAP in the stroma and this is associated with increased local tumour invasion, increased risk of lymph node metastasis and decreased survival." (PMID 39619326, 2024). "Fibroblast activation protein (FAP) is a known promoter of tumor development and is associated with poor clinical outcome for various cancer types." (PMID 38540158, 2024). "Simlukafusp alfa, a fusion protein, combines fibroblast activation protein (FAP) targeting with interleukin-2 variant (IL2v), focusing primarily on modifying the tumor microenvironment." (PMID 38558814, 2024). "Given that FAP is overexpressed on the surface of cancer-associated fibroblasts, the FAP-mediated retention of simlukafusp alfa in the tumor microenvironment is expected to provide improved antitumor activity." (PMID 39140264, 2024).